KISS1 (KiSS-1 metastasis suppressor)
Diseases named in the same sentence as KISS1 in open-access papers (continued):
Sharing a sentence is not in itself a finding about the gene and the disease.
cancer (78 papers, 2008 to 2026). A tumor composed of atypical neoplastic, often pleomorphic cells that invade other tissues. "G protein-coupled receptor 54 (GPR54) plays a role in cancer development by interacting with its endogenous ligand kisspeptin encoded by the KISS1 gene." (PMID 41771825, 2026). "KISS1, the metastasis‐suppressor gene, encodes kisspeptins which inhibits migration and proliferation of cancers." (PMID 34096173, 2021). "Kisspeptins are proteins encoded by the KISS1 gene that have been initially described to inhibit metastases in cancer and induce secretion of gonadotropin-releasing hormone (GnRH), but recently, an increasing role in immunomodulatory effects has been described." (PMID 40629459, 2025). "Emerging evidence highlights the pivotal role of KISS1 in cancer metastasis; however, there remains a dearth of pancancer analyses, particularly concerning immunotherapy." (PMID 41523580, 2026). "First, we confirmed that KISS1 was highly expressed in most cancers, except for KIRP, KIPAN, and LUSC." (PMID 41523580, 2026). "Our study revealed a noteworthy disparity between KISS1 expression at the mRNA and protein levels, indicating potential posttranslational modifications within cancer cells." (PMID 41523580, 2026). "To obtain the expression status of KISS1 in pancancer, we analyzed 33 cancers based on TCGA database." (PMID 41523580, 2026). "According to the expression levels of KISS1, all the cancer cases in TCGA and GEO were divided into two groups: high‐ and low‐expression groups." (PMID 41523580, 2026). "Within TCGA project, high expression of KISS1 contributed to a poor prognosis of OS for cancers of KIRP, KIRC, and LUAD." (PMID 41523580, 2026). "From the broader cancer biology perspective, KiSS-1 functions as a metastasis suppressor through multiple complementary mechanisms." (PMID 41567980, 2025). "Aligned with its role in the development and regulation of cancers, KISS1 and its receptor are also found in a number of human cancers including breast and prostate, where they can serve as both prognostic biomarkers and therapeutic targets." (PMID 38599822, 2024). "KiSS1 has been reported to down-regulate the matrix metalloproteinases and in such a way to inhibit metastasis of cancer cells." (PMID 37790750, 2023). "Kiss1 is a cancer suppressor gene, well-known to inhibit the metastasis of malignantmelanomas and breast cancer, often by inhibiting chemotaxis and invasion." (PMID 36098456, 2023). "Intraperitoneal and pulmonary metastasis is inhibited by kisspeptin 1 (KISS1), as shown in xenograft models of several cancer types, such as ovarian, breast and melanoma cancers." (PMID 36430404, 2022). "To date, most of the mechanisms that mediate the regulation of KISS1 gene expression are identified in the hypothalamic context of animal models and cancers." (PMID 35101033, 2022). "Regarding the conducted studies on the role of KISS1, its role as an inhibitor of metastasis and proliferation in cancers has identified the KISS1 as a promising molecular target for the management of cancer progression and migration." (PMID 34096173, 2021). "Nowadays, the regulatory role of KISS1 in the progression of several cancers, especially tumorigenesis and metastasis, has come to light; however, its role has not been fully elucidated, so determining its exact role can be beneficial in types of cancers." (PMID 34096173, 2021). "Screening for cancer-related genes downregulated by DNA-methylation in gastric cancer identified the induced expression of KiSS-1 along with its receptor GPR54 upon treatment with 5-aza-2’-deoxycytidine/decitabine." (PMID 32503267, 2020).
cancer (continued). "The gene set enrichment analysis revealed that these interacting proteins also interacted with cancer-related proteins, including KISS1, TIMP2, MMP11, IGFBP1, EGFR, and CDKN1C." (PMID 32117443, 2020). "The possible epigenetic modulation of KISS1 in cancer has been investigated and, although the available data are still relatively few, research in the field is promising for cancer prevention, diagnosis, and treatment." (PMID 31336647, 2019). "CpG islands are present in the KISS1 promoter and in cancer the hypermethylation of the KISS1 promoter results in protein hypoexpression." (PMID 31336647, 2019). "KISS1 (commonly classified as a metastasis suppressor gene) exerts anti-cancer roles in many cancers (reviewed)." (PMID 30046386, 2018). "Originally, the KiSS1 gene is identified as a metastasis suppresser gene due to the ability of KP-54 to inhibit cancer cell metastasis." (PMID 29614094, 2018). "Acquirement of metastatic potential through KISS1 activity has been identified as a central feature in a variety of cancers, including primary CRC." (PMID 30602942, 2018). "Expression of KISS1 has also been correlated with poor survival in human cancers, however, expression patterns differ between different types of malignancies." (PMID 30602942, 2018). "KISS1R binds kisspeptins, peptide products of the KISS1 gene and in numerous cancers, this signaling pathway plays anti-metastatic roles." (PMID 28422142, 2017). "Our results provide foundations for future exploitation of recombinant LAB for in vivo delivery of the proteinaceous agent KiSS1 in cancer therapy." (PMID 27287327, 2016). "KiSS1 and its receptor KiSS1R have been studied for their metastasis-suppressing ability in numerous human cancer cells." (PMID 27287327, 2016). "In this study, we further verified that L. lactis was an excellent candidate as a delivery vector that can be engineered to secrete the anti-cancer peptide KiSS1 using the nisin-inducible expression system." (PMID 27287327, 2016). "KISS1 is one of the major metastasis suppressors that is inactivated in the majority of cancer types." (PMID 27145368, 2016). "KISS1/KISS1R system has also been shown to be active in many cancer cell types with profound anti-metastatic action." (PMID 27101408, 2016). "It is reported that the downregulation of MMP-9 via GPR54 and ERK-MAPK signaling pathway was involved in the inhibitory effect of KiSS1 on the migration and invasion of cancer cells." (PMID 27287327, 2016). "KiSS-1 peptide, a cancer suppressor, plays a critical role in inhibiting cancer metastasis and its activity has been confirmed by direct administration." (PMID 27287327, 2016). "KiSS1 functions as a metastasis suppressor in various cancers, and epigenetic silencing of KiSS1 increases the metastatic potential of cancer cells." (PMID 25272010, 2014). "In 1996, kisspeptin, the product of the Kiss1 gene, was first discovered as an anti-metastatic peptide in human carcinoma." (PMID 24552453, 2014). "This suppression of metastasis by Kiss1 gene was subsequently demonstrated in various cancer cell-lines as well as in animal and human cancer experiments." (PMID 23696833, 2013). "Previous findings have shown that KISS1 acts as a metastasis suppressor in numerous cancers in humans." (PMID 21738726, 2011). "In numerous cancers such as melanoma, pancreatic cancer, and gastric carcinoma, KISS1/GPR54 signaling is anti-metastatic." (PMID 21738726, 2011). "Therefore, the role in cancer metastasis of KISS1 is context‐dependent, and further studies are needed to elucidate the underlying mechanisms." (PMID 41523580, 2026). "Therefore, we further analyzed the correlation of KISS1 expression with eight immune checkpoint pathway genes in diverse cancer types using TCGA." (PMID 41523580, 2026). "The difference in the expression of KISS1 among various cancers may suggest the biomarker potential of KISS1, and we further tested this potential in the background of clinical and metastatic stages." (PMID 41523580, 2026).
cancer (continued). "This may partly explain the controversial role of KISS1 in the regulation of metastasis in various cancers." (PMID 41523580, 2026). "KISS1 knockdown significantly reduced cancer cell signal at 2 weeks in the hind limbs of nude mice." (PMID 41523580, 2026). "Accordingly, the conclusions presented by the three scores may provide a conceptual map of immune and stromal cells in various cancers, which may explain the differential role of KISS1 in the metastasis of malignancies." (PMID 41523580, 2026). "KISS1 functions as a metastasis suppressor gene in many cancers." (PMID 35349482, 2022). "KISS1 or KISS1R is likely to be an independent prognostic factor in certain cancer types." (PMID 35117986, 2021). "Interestingly, BRMS1 and KiSS-1 can decrease NF-κB-mediated target gene expression and thus suppress cancer cell motility and invasiveness." (PMID 32503267, 2020). "In particular, they assessed that the expression levels of KiSS-1 and KiSS-1R were lower in cancer tissues compared to normal tissues; moreover, KiSS-1 and KiSS-1R expression was lower in patients with advanced stage compared to patients with low stage of NSCLC." (PMID 29760678, 2018). "Aberrant expression of KiSS-1 could decrease or lower its ability to inhibit cancer cell invasion and metastasis." (PMID 30021598, 2018). "KiSS-1 is considered a metastatic suppressor in many cancers." (PMID 30021598, 2018). "Thus, as found for many human cancer related proteins and as suggested also by its amino acid sequence, human KISS1 is an intrinsically disordered protein." (PMID 28207895, 2017). "However, therapeutic programs using KISS1 agonists to modulate KISS1R-expressing neurons likely activate KISS1/KISS1R signaling in individual cancer cells." (PMID 27015368, 2016). "We therefore hypothesized that expression of biologically active KiSS1 would inhibit proliferation and migration of different kinds of cancer cells." (PMID 27287327, 2016). "Our study suggests that L. lactis is an ideal vector for the secretion expression of anti-cancer agent KiSS1, which maybe a promising strategy for cancer therapy in the future." (PMID 27287327, 2016). "Kiss-1 and Kiss-1R have been suggested as a novel pair of metastasis suppressors in most cancers." (PMID 25260785, 2014). "Thus, cancer cells incapable of KISS1 processing should still be suppressed for metastasis as long as secretion is unabated." (PMID 24454770, 2014). "In human cancers, metastasis suppressor proteins such as E-cadherin and KiSS-1/metastin may undergo proteolytic cleavage, subsequently losing their functional capabilities." (PMID 23634903, 2013). "Thus, KISS1 may undergo ubiquitination in a context‐dependent manner, which may explain the difference in its effect on metastasis in different cancers." (PMID 41523580, 2026). "Besides, CD274 had a relatively strong correlation with KISS1 and was mainly negatively related in pancancer, indicating that CD274 may be a potential checkpoint in cancers that have abnormal KISS1 expression." (PMID 41523580, 2026). "Therefore, for mesenchymal cells, we would expect that the reduction of the slow viscous rate constant after AG879 treatment that reduces RB1 and KISS1 expression may lead to increased cancer cell migration and metastasis." (PMID 41028875, 2025). "Specifically, CTD-2218G20.2 was predicted to interact with 86 proteins (Pearson correlation coefficient, PCC > 0.3), some of which, including PSG4, PSG5, and PSG7, could also interact with cancer-related proteins, including KISS1, TIMP2, MMP11, IGFBP1, EGFR, and CDKN1C." (PMID 32117443, 2020).
cancer (continued). "According to various clinical data, a decrease in KiSS-1 and/or GPR54 expression has been shown to be associated with poorer prognosis in cancer patients and, therefore, the expression of KiSS-1 and/or GPR54 might be useful predictive biomarkers in medical outcomes." (PMID 29662466, 2018). "Likewise, in polymorphisms and gene expression studies it has been shown that KiSS1 low mRNA expressions correlate with venous invasion, advanced clinical stage, occurrence of metastasis, and recurrence in patients with different types of cancer." (PMID 25810563, 2015). "Moreover, we do not know the biological significance of these polymorphisms in cancer cells, and there is no information about other gene variants described in KiSS1." (PMID 25810563, 2015). "Higher expression of KISS1 may also sensitize cancer cells for chemotherapy." (PMID 24528603, 2014). "In summary, we found a consistent trend that KISS1 negatively regulates TME in most cancers from TCGA, and KISS1 expression and immune infiltration were both highly expressed in cancers such as PRAD." (PMID 41523580, 2026). "The KISS1 gene and KISS1 receptor (KISS1R) display variable mRNA expression levels in different cancers and at different cancer stages." (PMID 39775975, 2025). "This revealed peaks for TEAD1 and TEAD4 on both KISS1 and CXCL8 promotors, suggesting that within cancer cells, TEAD transcription factors facilitate the expression of genes both up‐ and down‐regulated on NF2 loss." (PMID 36740402, 2023). "Kisspeptins (KPs, KISS1) and their receptor (KISS1R) play a pivotal role as metastasis suppressor for many cancers." (PMID 38256878, 2023). "A PPI network indicated the GNRH1 interacted with several important cancer-related proteins, including AKT1/3, MAPK1/3, and KISS1." (PMID 35646056, 2022). "In previous studies, the Kiss1/GPRS4 system has been shown to play an important role in mammalian reproductive function and cancer biology." (PMID 36231110, 2022). "In the future, additional experiments will be required to explore the role of KISS1 and KISS1R in other cancers and to determine the exact mechanism of their function." (PMID 35117986, 2021). "P234 is an antagonist of KiSS1, a downstream target of the canonical TGFβ/SMAD2 pathway in this cancer type." (PMID 33498521, 2021). "Given their roles, KISS1, KPs and KISS1R represent important molecules in the development of novel therapies and/or as prognostic markers in treating cancer." (PMID 30123188, 2018). "Firstly, Kisspeptin-1 (KiSS1) and its G protein coupled receptor GPR54 are widely present in cancer and their involvement in both carcinogenesis and metastasis has been intensively documented." (PMID 28469531, 2017). "Early studies showed the ability of MT5-MMP to proteolytically activate MMP-2 and to process KiSS-1 protein and KISS-1-derived decapeptide metastin, which overall promotes cancer progression." (PMID 27349644, 2016). "Several studies have described a prognostic value of KISS1 and KISS1R expression in tumors across a variety of cancer types and a role in metastasis and trophoblast invasion, both invasive processes." (PMID 19536297, 2009). "Kisspeptin-1 (KISS-1) inhibits cell motility, proliferation, invasion, and metastasis in cancers." (PMID 36769293, 2023). "Although the role of KiSS1 in cancer is not completely clarified, an involvement in controlling metastasis dissemination and response to cisplatin (cDDP) has been proposed." (PMID 37790750, 2023). "KiSS-1, which was originally identified in non-metastatic melanoma by analysis of subtractive hybridization, is widely considered a critical cancer metastasis suppressor gene." (PMID 30021598, 2018). "The other common MS genes, including CD28, KISS1, NME2, BRMS1, shared in over 10 cancer types." (PMID 26486520, 2015). "Given all the previous studies, there are no studies on KISS1 in the entire cancer spectrum." (PMID 41523580, 2026).
cancer (continued). "Although a binding assay could not confirm that ubiquitination of KISS1 within cells contributes to the influence of protein stability, this indeed indicates the promising role of ubiquitination of KISS1 in cancer therapy." (PMID 41523580, 2026). "Interestingly, for six genes (KISS1, CXCR4, PSMB9, ABCB1, FGF2, and IL6) found to be up-regulated along with GCS, their overexpression pursuant to platinum-agent treatments in patients promoted resistance to those same agents in cancers." (PMID 40507922, 2025). "Despite the fundamental role of kisspeptin‐signalling in reproductive function, early study focused on its involvement in cancer biology when in 1996 the kisspeptin gene (KISS1 in humans and Kiss1 in nonhumans) was first discovered as a metastasis suppressor gene in human melanoma cell lines." (PMID 36262016, 2022). "Although these results were obtained from studies on the Kiss1/GPR54 system and cancer, given the existence of tissue interactions, we can speculate that Kiss1/GPR54 system is involved in the regulation of skeletal muscle Ca2+ concentration; this hypothesis needs to be confirmed by further studies." (PMID 36231110, 2022). "Since the relationship between Let‐7i with several target genes including MMP9, C‐Myc and PTEN has been evaluated in different types of cancer, this study focused on KISS1, a newly identified target gene in which there was no study to determine its association with Let‐7i." (PMID 34096173, 2021). "The induction of KiSS-1/GPR54 upon DNA-demethylation was confirmed in endometrial cancer and might serve as therapeutic strategy to inhibit metastasis formation in additional cancers." (PMID 32503267, 2020). "There is currently no confirmed data on the methylation status of KiSS-1 and GPR54 genes in cancer, but the study of this epigenetic modification could potentially elucidate the variations in expression patterns examined in different studies on human cancer tissues, as subsequently described." (PMID 29662466, 2018).
infection (4 papers, 2019 to 2025). The state of being infected such as from the introduction of a foreign agent such as serum, vaccine, antigenic substance or organism. "Infection of CRC cells with sh-UHRF1 promoted the expression of the KISS1 protein and inhibited the expression of PI3K/NF-κB signaling pathway-related proteins." (PMID 31803739, 2019). "After infection with the STAT4 lentiviral vector (LV-STAT4) in follicles of mice, the expression of STAT4 in ovaries of mice significantly increased, and the expression of KISS1 was significantly decreased." (PMID 40214477, 2025).
KISS1 also shares sentences with these, for which no sentence is quoted: type 2 diabetes (4 papers); female infertility (3); metabolic disorders (3); cervical cancer (2); esophageal squamous cell carcinoma (2); head and neck squamous cell carcinoma (2); hyperandrogenism (2); Impaired glucose tolerance (2); adenomyosis (1); adrenocortical carcinoma (1); Alzheimer disease (1); amenorrhea (1); anovulation (1); atherosclerosis (1); benign breast disease (1); benign prostate hyperplasia (1); benign tumors (1); breast adenocarcinoma (1); cardiac hypertrophy (1); cardiovascular disease (1); Cerebellar hypoplasia (1); chronic kidney disease (1); emotional instability (1); Epididymis (1); esophageal cancer (1); glioma (1); gonadotroph adenomas (1); Gonadotropin deficiency (1); head and neck cancer (1); heart diseases (1).
A further 23 diseases each share a sentence with KISS1 in 1 paper.